PAK1 (p21 (RAC1) activated kinase 1)
Diseases named in the same sentence as PAK1 in open-access papers (continued):
Sharing a sentence is not in itself a finding about the gene and the disease.
GEJ adenocarcinoma (1 paper, 2013). "Accordingly, low expression of PAK1 is strongly associated with prolonged survival of GEJ adenocarcinoma patients." (PMID 24236193, 2013). "Results revealed PAK1 overexpression as an independent high-risk predictive indicator for the prognosis of GEJ adenocarcinoma patients." (PMID 24236193, 2013). "PAK1 overexpression may serve as an independent high-risk prognostic predictor that holds therapeutic promise for GEJ adenocarcinoma." (PMID 24236193, 2013). "Our cancer-spectrum analysis reveals that PAK1 expression in GEJ adenocarcinoma is higher than in most other forms of tumors, suggesting that PAK1 overexpression is selective for this type of cancer." (PMID 24236193, 2013). "Here we employed multiple approaches to provide the first comprehensive analysis of PAK1 in a large series of 176 samples from patients with primary resected GEJ adenocarcinoma and the relevant microarray datasets." (PMID 24236193, 2013). "Altogether, these findings clearly indicate that PAK1 is upregulated in tumor tissues compared to normal controls, in agreement with the oncogenic potential of PAK1 in GEJ adenocarcinoma." (PMID 24236193, 2013). "We then examined the relationship of PAK1 expression with the clinicopathological features in GEJ adenocarcinoma." (PMID 24236193, 2013). "We used a data mining approach and identified the p21 protein-activated kinase 1 (PAK1), an oncogene and drugable protein kinase, to be among the most promising targets for GEJ adenocarcinoma." (PMID 24236193, 2013). "In conclusion, we utilize several avenues to characterize the PAK1 expression profile in the tumor progression of GEJ adenocarcinoma." (PMID 24236193, 2013). "Immunohistochemistry revealed PAK1 overexpression in 72.6% of primary GEJ adenocarcinomas (n = 113)." (PMID 24236193, 2013). "We further investigated the expression profile of PAK1 in GEJ adenocarcinoma by utilizing immunohistochemistry." (PMID 24236193, 2013). "Although PAK1 has been studied in gastrointestinal cancers, the role of PAK1 in GEJ adenocarcinoma remains missing." (PMID 24236193, 2013). "Since PAK1 is a well-known oncogenic protein in many types of cancers, we weighed the importance of PAK1 in GEJ adenocarcinoma against other cancers." (PMID 24236193, 2013). "In order to assess the prognostic impacts of PAK1 expression on the outcome of GEJ adenocarcinoma patients, Kaplan-Meier survival analyses were performed." (PMID 24236193, 2013). "PAK1 expression could serve as a prognostic predictor that holds therapeutic promise for GEJ adenocarcinoma." (PMID 24236193, 2013). "Overall, our results suggest that PAK1 expression is closely associated with tumor invasion and LN metastasis rather than cell proliferation in GEJ adenocarcinoma." (PMID 24236193, 2013). "Thus, therapeutic strategy targeting PAK1/HER-2/EGFR network holds promise for the treatment of GEJ adenocarcinoma." (PMID 24236193, 2013). "Since PAK1 is an oncogene and drugable protein kinase, targeting PAK1 may represent an avenue for improvement of GEJ adenocarcinoma therapy." (PMID 24236193, 2013). "Together, these data demonstrate that PAK1 overexpression is associated with malignant properties mainly relevant to invasion and LN metastasis and thus support the hypothesis that the altered PAK1 may contribute to tumor progression of GEJ adenocarcinoma." (PMID 24236193, 2013). "Thus, our study underscores the importance of PAK1 as a prognostic biomarker that also holds great therapeutic promise for GEJ adenocarcinoma." (PMID 24236193, 2013). "Yet despite such great promise, PAK1 is mostly unknown in GEJ adenocarcinoma." (PMID 24236193, 2013). "Thus the significance of PAK1 in GEJ adenocarcinoma in this study may be largely confined to the type II and III, which are more prevalent in Asian populations." (PMID 24236193, 2013).
GEJ adenocarcinoma (continued). "Given that PAK1 has been reported to regulate cell proliferation in several cancers, we further examined if PAK1 is correlated with PCNA, a cell proliferation marker, in GEJ adenocarcinoma." (PMID 24236193, 2013). "A cohort of GEJ adenocarcinomas (n = 20) assayed by immunoblot analysis demonstrated that 75% of GEJ adenocarcinoma tissues (15/20) showed higher PAK1 expression than in the adjacent noncancerous tissues (P<0.001)." (PMID 24236193, 2013). "Our data also support the notion that PAK1 is an important node in the PAK1/HER-2/EGFR network and may be a targetable molecule for GEJ adenocarcinoma." (PMID 24236193, 2013). "In line with this hypothesis, analysis of the silicon data set identified a close correlation between PAK1 and HER-2 transcripts in GEJ adenocarcinoma, and this was further validated by IHC analysis in surgical specimens of GEJ adenocarcinoma (n = 46)." (PMID 24236193, 2013).
Granuloma (1 paper, 2020). A compact, organized collection of mature mononuclear phagocytes, which may be but is not necessarily accompanied by accessory features such as necrosis. "In addition, the hepatic PAK1 had a significant positive correlation with the area of granuloma in the livers from Sjaponicum‐infected WT mice." (PMID 33124146, 2020).
hair loss (1 paper, 2017). "PAK1 (p21-activated kinase 1) is an emerging target for the treatment of hair loss (alopecia) and cancer; therefore, the search for PAK1 blockers to treat these PAK1-dependent disorders has received much attention." (PMID 28098826, 2017). "Regarding the mechanism underlying their action, we hypothesized that the anti-alopecia and anticancer activities of these compounds could be attributed to the inhibition of the oncogenic/aging kinase PAK1." (PMID 28098826, 2017). "In this study, we evaluated the anti-alopecia and anticancer effects of PAK1 inhibitors isolated from Alpinia zerumbet (alpinia) in cell culture." (PMID 28098826, 2017). "Since PAK1 is associated with both cancer and hair loss, and alpinia is a useful source of PAK1 inhibitors, we isolated and evaluated the effects of PAK1-blocking bioactive compounds from alpinia against alopecia and cancer in the present study." (PMID 28098826, 2017). "Taken together, in the present study, KOG, labdadiene, and MTD demonstrated anti-alopecia activity, which could be the result of blocking of PAK1 by these compounds." (PMID 28098826, 2017).
hearing loss (1 paper, 2020). "However, our observation that Pak1 gene expression was up-regulated in the cochlea submitted to TNFα blockade gene silencing not only is a novelty finding but also can putatively suggest that its up-regulation may promote cell survival after the noise-induced hearing loss in our experimental model." (PMID 32294929, 2020).
Hepatitis (1 paper, 2023). Inflammation of the liver. "It is worth noting that PAK1 promotes the development of HBV, hepatitis E virus, parasite, and autoimmune-related hepatitis while inhibiting HCV-induced hepatitis." (PMID 36672500, 2023).
hypertrophic cardiomyopathy (1 paper, 2019). A condition in which the myocardium is hypertrophied without an obvious cause. "PAK1 regulates excitability and contractibility of cardiomyocytes; with over-expression improving cardiac function in mice, and deletion worsening hypertrophic cardiomyopathy." (PMID 31170930, 2019).
immune deficiencies (1 paper, 2023). "Thus, Pak1-knockout mice have been generated and display MAPK signaling defects and, accordingly, present slight immune deficiencies." (PMID 36937657, 2023).
Impaired glucose tolerance (1 paper, 2025). An abnormal resistance to glucose, i.e., a reduction in the ability to maintain glucose levels in the blood stream within normal limits following oral or intravenous administration of glucose. "PAK1 levels are reduced by ~80% in type 2 diabetic human islets, as well as in frank and impaired glucose tolerance mouse islets." (PMID 39404845, 2025). "However, whether PAK1 enhancement in mice with impaired glucose tolerance carries the capacity to mitigate functional beta cell mass loss, and by what molecular mechanisms, remains to be elucidated." (PMID 39404845, 2025).
inflammatory breast carcinoma (1 paper, 2016). An advanced, invasive breast adenocarcinoma characterized by the presence of distinct changes in the overlying skin. "In addition, a recent study has shown that PAK1 overexpression correlates with the expression of FA/BRCA genes in inflammatory breast cancer samples." (PMID 27740936, 2016).
invasive breast carcinoma (1 paper, 2015). A carcinoma that infiltrates the breast parenchyma. "In these studies, E2F1 expression was only slightly or not significantly induced in tumor tissue relative to matched normal tissue, with the only exception being the invasive breast cancer study in which a 2.16-fold up-regulation of Pak1 correlated with a 2.7-fold up-regulation of E2F." (PMID 26555075, 2015).
Kaposi's sarcoma (1 paper, 2023). A malignant neoplasm characterized by a vascular proliferation which usually contains blunt endothelial cells. "For example, Hepatitis B virus X protein and KSHV vFLIP control PAK1 and COX-2, allowing infected cancer cells to circumvent anoikis and prevent and inhibit metastasis in HCC and Kaposi's sarcoma, respectively." (PMID 38144298, 2023).
malignant meningioma (1 paper, 2015). "NF2-null malignant meningioma KT21-MG1-Luc5D cells (hereafter referred to as KT21), were stably transduced with either empty virus or a virus encoding a Pak1 or Pak2 shRNA construct." (PMID 25596744, 2015).
mastocytosis (1 paper, 2015). A clonal myeloproliferative neoplasm characterized by the proliferation and accumulation of neoplastic mast cells in one or multiple organs or organ systems. "It will be interesting to elucidate the LIC containing fraction in the HSC pool that triggers KIT D814V induced mastocytosis, which subsequently can be targeted using PAK1 inhibitors." (PMID 26158763, 2015).
medulloblastoma (1 paper, 2013). A malignant, invasive embryonal neoplasm arising from the cerebellum. "Comparable to these results, down-regulation of PAK1 in medulloblastoma cells did not alter platelet-derived growth factor mediated activation of ERK and a study in osteoclast cells similarly showed that PAK1 does not modulate Raf-mediated MEK activation by macrophage colony stimulating factor." (PMID 24040362, 2013).
metastatic cancer (1 paper, 2019). A carcinoma which has spread from the original site of growth to another anatomic site. "PAK1 depletion in metastatic cancer cells did not impact invadopodia formation but significantly impaired invadopodia disassembly in vivo." (PMID 30651600, 2019).
muscle disorders (1 paper, 2019). "However, variants that alter expression levels of PAK1 and/or PAK2 in humans could contribute to muscle disorders as modifier loci." (PMID 30791960, 2019).
myxofibrosarcoma (1 paper, 2023). A malignant fibroblastic neoplasm arising from the soft tissue. "However, the clinical and functional relevance of PAK1 and associated signaling remains undefined in myxofibrosarcoma." (PMID 37564209, 2023). "In this context, it is sobering to rethink the adjuvant administration of recombinant CSF2 to ameliorate therapy-induced neutropenia in CSF2-releasing cancers 49, such as myxofibrosarcomas with overexpressed and activated PAK1, which is at risk of detrimental cancer-promoting effect." (PMID 37564209, 2023). "The consistent in vitro pro-angiogenic attribute of PAK1 seen in genetically manipulated myxofibrosarcoma cell models prompted us to explore the potential angiogenic mediator(s) and pertinent regulatory underpinning." (PMID 37564209, 2023). "Our in vitro evidence indicated that CSF2 is a potential PAK1-driven angiogenic factor self-produced by myxofibrosarcoma cells (Figure-2)." (PMID 37564209, 2023). "Myxofibrosarcoma specimens were analyzed for the levels of PAK1, phospho-PAKT423, CSF2 and microvascular density (MVD) and those of PAK1 gene and mRNA." (PMID 37564209, 2023). "Using myxofibrosarcoma cells, we explored the oncogenic underpinning of PAK1 with genetic manipulation and a pan-PAK inhibitor (PF3758309)." (PMID 37564209, 2023). "Of notice, these characteristics provided a rationale to identify aggressive myxofibrosarcomas, which were significantly PAK1-amplified and potentially actionable due to the intrinsic genetic vulnerability in angiogenesis." (PMID 37564209, 2023). "Our findings provide not only prognostic insight into future risk stratification but also a novel biomarker-guided therapeutic approach to targeting angiogenesis in aggressive myxofibrosarcomas which harbor the vulnerable PAK1/STAT5B/CSF2 proangiogenic axis." (PMID 37564209, 2023). "Using TMA-assembled primary myxofibrosarcoma tissues, we validated the clinical relevance of the PAK1 gene copy number, PAK1 mRNA abundance, and immunoexpression levels of whole-cell PAK1, whole-cell and nuclear p-PAK1T423, and cytoplasmic CSF2." (PMID 37564209, 2023). "Conclusively, the nuclear entry of overexpressed/activated PAK1 endows myxofibrosarcomas with pro-angiogenic function, highlighting the vulnerable PAK1/STAT5B/CSF2 regulatory axis." (PMID 37564209, 2023). "Overexpressed PAK1 is recurrently amplification-driven in myxofibrosarcomas in which it confers pro-proliferative, pro-metastatic, and pro-angiogenic phenotypes." (PMID 37564209, 2023). "Collectively, our findings shed promising light on future management of myxofibrosarcomas with the vulnerability of PAK1-driven angiogenesis, either alone or in combination with conventional chemotherapy." (PMID 37564209, 2023). "Using confocal immunofluorescence microscopy, we observed varying but distinctive nuclear PAK1 localization in parent myxofibrosarcoma cells (Figure-S6A), commensurate with significant nuclear PAK1 immunoexpression in a subset of aggressive myxofibrosarcomas detailed below." (PMID 37564209, 2023). "Upon nuclear entry together with STAT5B, PAK1 co-transactivated the pro-angiogenic CSF2 gene, encoding granulocyte-macrophage colony stimulating factor 2 (a.k.a GM-CSF), to increase CSF2 expression, hence enhancing angiogenesis in myxofibrosarcomas." (PMID 37564209, 2023). "Through conferring the potent pro-angiogenic capacity, PAK1 overexpression/activation may represent a viable druggable target of myxofibrosarcomas." (PMID 37564209, 2023). "These clues further infer a question of whether, in a positive feedback loop, overproduced CSF2 in myxofibrosarcoma cells depends on nuclear PAK1 to invigorate the activity of JAK2/STAT5B cascade." (PMID 37564209, 2023). "However, in the input NMFH2 lysates, the phosphorylated tyrosine levels in pCMV6-PAK1T423E and pCMV6-PAK1 transfectants were similar, implying the involvement of threonine activation and tyrosyl phosphorylation to facilitate PAK1 nuclear entry in myxofibrosarcomas." (PMID 37564209, 2023).
myxofibrosarcoma (continued). "In primary myxofibrosarcoma samples, we clinically validated the whole-cell and nuclear expression of total PAK1 and its phosphorylated form (p-PAK1T423), which exhibited significant associations with PAK1 gene amplification, increases in mRNA abundance, grades and stages, and adverse outcomes." (PMID 37564209, 2023). "RSF1 gene is amplified in a significant subset of myxofibrosarcomas and resides on 11q13-14.1, where RSF1 and PAK1 are the only two significantly upregulated genes with gained copies in this region." (PMID 37564209, 2023). "In vitro, genetic ablations of PAK1 and CSF2, the CSF2-directed antibody, and pharmacological intervention with PF-3758309 inhibitor all significantly abrogated angiogenesis of myxofibrosarcoma." (PMID 37564209, 2023). "In myxofibrosarcoma cell models, the constitutively hyperactive PAK1T423E significantly increased the PAK1 tyrosine phosphorylation and PF3758309 enabled concomitant inhibition on the phosphorylated threonine and tyrosine of PAK1." (PMID 37564209, 2023). "To evaluate the biologic significance of PAK1 and its functional redundancy potentially overlapped with other members of PAK oncogene family, we first characterized three myxofibrosarcoma cell lines (OH931, NMFH1, NMFH2) for their endogenous expression levels of PAK1-4." (PMID 37564209, 2023). "First, through a focused reappraisal of myxofibrosarcomas relative to non-neoplastic tissues in the published GSE21122 dataset 5, we identified PAK1, alongside RSF only, as significantly upregulated in the mRNA abundance among candidates on 11q13-14.1 (Figure-1B)." (PMID 37564209, 2023). "Although PF3758309 is considered a pan-PAK inhibitor not targeting PAK1 alone 14, 33, this drug might indeed exert a notably specific repressive effect on PAK1-driven angiogenesis, an oncogenic attribute not redundantly phenocopied by PAK2-4, in myxofibrosarcomas at least." (PMID 37564209, 2023).
neurofibroma (1 paper, 2024). An intraneural or extraneural neoplasm arising from nerve tissues and neural sheaths. "CRISPRi suppression of NF2 in NF1-mutant NF95.11b neurofibroma cells induced PAK1 phosphorylation (pPAK1) without significantly affecting pMEK, pERK, or pAKT compared to sgNTC." (PMID 38216572, 2024).
neurofibrosarcoma (1 paper, 2020). A malignant tumor that arises from small cutaneous nerves, is locally aggressive, and has a potential for metastasis. "PAK1 is required for the malignant growth of RAS transformants in NF1 neurofibrosarcoma cell lines." (PMID 32858845, 2020).
oral cancer (1 paper, 2016). "Our study suggests that PAK1 plays a crucial role in the progression of oral cancer and represents a potential therapeutic target in OSCC." (PMID 27229476, 2016). "Studying the role of PAK1 and its substrates is likely to enhance our understanding of oral carcinogenesis and potential therapeutic value of PAKs in oral cancer." (PMID 27229476, 2016). "Further studies are required to bring out the mechanistic insights into the role of PAK1 in oral cancer progression." (PMID 27229476, 2016). "In this work, we investigated the role of PAK1 in oral cancer." (PMID 27229476, 2016). "Our results suggest that PAK1 is over-expressed in oral cancer cell lines." (PMID 27229476, 2016). "In brief, PAK1 plays a crucial role in OSCC progression and that studying the role of PAK1 could improve our understanding of oral carcinogenesis and in determining new therapeutic targets for oral cancer." (PMID 27229476, 2016).
osteoarthritis (1 paper, 2020). A noninflammatory degenerative joint disease occurring chiefly in older persons, characterized by degeneration of the articular cartilage, hypertrophy of bone at the margins and changes in the synovial membrane. "We found that the expression of PAK1 was significantly increased in chondrocytes treated with osteoarthritis-related factors." (PMID 31868209, 2020). "The level of PAK1 expression was measured by Western blot and quantitative real-time PCR in articular cartilage from osteoarthritis model rats and patients with osteoarthritis." (PMID 31868209, 2020). "Increased expression of PAK1 was also observed in knee articular cartilage samples from patients with osteoarthritis and osteoarthritis model rats." (PMID 31868209, 2020). "The purpose of the present study was to determine the potential role of PAK1 in osteoarthritis." (PMID 31868209, 2020). "Results of the present studies demonstrated that PAK1 might play an important role in the pathogenesis of osteoarthritis." (PMID 31868209, 2020).